MYCN (MYCN proto-oncogene, bHLH transcription factor)
Diseases named in the same sentence as MYCN in open-access papers (continued):
Sharing a sentence is not in itself a finding about the gene and the disease.
neuroblastoma (continued). "We then asked whether PHA-680626 treatment differentially affects MYCN amplified versus MYCN non-amplified neuroblastoma cells." (PMID 34884931, 2021). "Higher expression of Lewis antigens in neuroblastoma MYCN-amplified cell lines and patient samples could be a consequence of the overexpression of SiaTs, including ST3Gal3/4/6, compared to MYCN-non-amplified counterparts." (PMID 34975914, 2021). "However, MYCN non-amplified younger neuroblastoma patients had significantly favorable prognosis than MYCN non-amplified older neuroblastoma patients in TARGET, GSE49710 and GSE85047 datasets." (PMID 34116676, 2021). "And MYCN non-amplified pediatric neuroblastoma could be divided into several sub-groups by age and DST expression levels." (PMID 34116676, 2021). "Moreover, the prognostic significances of ALCAM, CACNA2D3, EPB41L4A and KIF1B in MYCN non-amplified pediatric neuroblastoma were not previously reported." (PMID 34116676, 2021). "However, MYCN amplification did not have any additional stratifying effect on outcome in patients with stage 4 neuroblastoma as 10y-EFS and OS was 50 ± 11% for both subgroups." (PMID 33540616, 2021). "However, extending trametinib use in neuroblastoma is challenged by the fact that constitutively active YAP overexpression induces resistance against trametinib in MAPK pathway-activated neuroblastoma cells via transcriptional activation of E2F and MYCN." (PMID 33467099, 2021). "Importantly, NDRG1 was found to be a positive prognostic factor in neuroblastoma, regardless of the MYCN amplification status, which suggests a functional role of NDRG1 on its own in addition to its role as a marker of N-MYC dysregulation in neuroblastoma." (PMID 35008802, 2021). "Misregulation of transcription, therefore, might attenuate BRCA1’s role in HR, although MYCN-amplified neuroblastoma cells do not show an increase of unrepaired DSBs." (PMID 33755171, 2021). "Therefore, functions and prognosis of DST in MYCN non-amplified neuroblastoma should be further studied." (PMID 34116676, 2021). "Thus, we investigated whether ATRA treatment affected the expression levels of members of the MYCN-driven adrenergic CRC and its extended regulatory network, which program the malignant cell state in most MYCN-amplified neuroblastoma cells." (PMID 34669465, 2021). "While the pro-tumourigenic or pro-metastatic role of EVs has been highlighted in different types of adult cancers it is not known whether they play a role in the context of MYCN-amplified neuroblastoma." (PMID 34847775, 2021). "Thus, our data and that from other studies indicate that a network composed of MYCN, E2F, PRC2, and KDM6B regulates cell proliferation and differentiation of neuroblastoma, highlighting the importance of KDM6B in coupling the two essential features of cancer cells." (PMID 34893606, 2021). "Focally amplified neuroblastomas have a negative prognosis, indistinguishable from uniformly amplified cases, suggesting that MYCN could promote a cross-talk between parts of the cancer with a different amplification status." (PMID 34847775, 2021). "In addition to investigating trans-acting factor promoting MYCN expression in MNA neuroblastoma in a 3’UTR- and miRNA-dependent manner, we also evaluated if the MYCN-3’UTR may serve as a miRNA decoy for MYCN-targeting miRNAs, as previously proposed." (PMID 34026620, 2021). "When analyzing the SNP-array data four different amplicons in the MYCN region in 2p24 as well as a 17q gain are identified, both of which are predictors of poor prognosis and aggressive disease in neuroblastoma that were not identified with sequencing data alone." (PMID 34545199, 2021). "Furthermore, a report from the Children’s Oncology Group showed correlation of metaiodobenzylguanidine (MIBG) avidity with high VMAT2 expression in neuroblastoma cases without MYCN amplification." (PMID 33465163, 2021).
neuroblastoma (continued). "These analyses are of utmost relevance in neuroblastomas without MYCN-amplification, TERT rearrangement, and ATRX alterations, as these neuroblastomas are most likely low-risk, but the detection of telomerase overexpression or ALT would still render them high-risk." (PMID 34442335, 2021). "They found in both datasets that tumors with 11q deletion showed a higher proportion of CD8+ and resting CD4+ memory T cells, as well as of resting (M0) and polarized macrophages (M1 and M2) compared to neuroblastoma tumors without 11q deletion, the majority of which show MYCN amplification." (PMID 33314654, 2021). "However, a comprehensive comparison of imaging to compare magnetic resonance imaging (MRI), US and luciferase signal between the Th-MYCN GEMM and several adrenal orthotopic models of neuroblastoma cell lines found that MRI was the most accurate in size measurements of the tumours." (PMID 33808071, 2021). "However, there were only 12 genes were down-regulated in MYCN non-amplified younger neuroblastoma patients." (PMID 34116676, 2021). "The rationale for adopting this strategy was that our recent report found that including the genetic biomarker MYCN to CSV+ CTC positivity boosted the accuracy of predictions of non-relapse from 95% to 100% in neuroblastoma patients who were in remission and receiving maintenance therapy." (PMID 34956881, 2021). "Furthermore, using multivariate cox regression, we determined the correlations of age, ALCAM, CACNA2D3, DST, EPB41L4A or KIF1B expression in the prediction of the clinical overall survival of MYCN non-amplified neuroblastoma patients." (PMID 34116676, 2021). "Our analysis revealed that MYCN non-amplified neuroblastoma was heterogeneous and could be divided into sub-groups based on the age at initial neuroblastoma diagnosis or the expression levels of DST." (PMID 34116676, 2021). "MYCN non-amplified neuroblastoma is a heterogeneous disease and could be divided into sub-groups based on age or the expression levels of ALCAM, CACNA2D3, DST, EPB41L4A and KIF1B." (PMID 34116676, 2021). "Notably, depletion of KDM6B led to MYCN and C-MYC reduction in neuroblastoma cells." (PMID 34893606, 2021). "Our findings support a potential interplay between MYCN and c-MYC upon glutamine deprivation, and we initially sought to investigate the co-expression of CSC-related genes such as ALDH1A1 and ALDH1A3 with MYC member expression in the paediatric neuroblastoma patient data from the TARGET study." (PMID 32483461, 2020). "For instance, enhancer hijacking that repositions a super enhancer close to the affected genes through chromosomal translocation accounts for the high level of C-MYC or N-MYC expression in some neuroblastoma cells without MYCC amplification or without a high MYCN copy number, respectively." (PMID 33614505, 2020). "In the present study, using published TARGET and GEO datasets, we comprehensively analyzed the differentially expressed genes in neuroblastoma patients with or without MYCN amplification, and identified the critical signaling pathways and transcription factors involving MYCN regulation." (PMID 32593299, 2020). "However, given MYCN expression is driven by the TH promoter rather than by genomic amplification it is not a true model of MYCN amplified neuroblastoma." (PMID 32577161, 2020). "The association with TGF-beta receptor (although only based on sequence homology), possible regulation by MYCN, a relation to neuroblastoma and the selective detection in gonadotroph non-neoplastic and tumour cells, make this protein relevant for further studies and characterisation." (PMID 33396509, 2020). "We selected IMR-32, ACN and SH-SY5Y cell lines due to their different genomic characteristics: IMR-32 display MYCN (v-myc myelocytomatosis viral related oncogene, neuroblastoma derived) amplification, whereas ACN and SH-SY5Y do not, and SH-SY5Y exhibit strong c-MYC protein expression." (PMID 32737364, 2020).
neuroblastoma (continued). "Given the complexity of the PLAGL2 transcriptome indicated in the published studies, it is reasonable to speculate that MYCN is not the sole transcription target that mediates the function of PLAGL2 in neuroblastoma cells." (PMID 32087738, 2020). "In neuroblastomas with MYCN amplification or high MYCN levels without MYCN amplification, the positive regulatory loop of the MYCN-PRMT1 axis may promote a MYCN-driven oncogenic program whereas PRMT1-mediated activation of ATF5 may lead to enhanced survival." (PMID 32415090, 2020). "And neuroblastoma patients without MYCN amplification and low EIF4G1 expression had best prognosis." (PMID 32593299, 2020). "Interestingly, similar pathways that are used to avoid MYC transduction in iPS generation are potentially involved in the tumorigenesis of MYCN non-amplified neuroblastomas." (PMID 33585251, 2020). "For MYCN non-amplified neuroblastoma, c-Myc is predominantly responsible for NB tumor progression." (PMID 33324552, 2020). "A subset of genes that are normally induced in MYCN-amplified neuroblastomas also may have failed to be activated in the ATRX-mutant neuroblastomas owing to the DNA and/or histone modifications." (PMID 32060267, 2020). "Neuroblastoma patients without MYCN amplification and low EIF4G1 expression had best prognosis." (PMID 32593299, 2020). "The four UHR-NB upregulated genes (ADAM22, GAL, KLHL13 and TWIST1) were all upregulated in MYCN amplified neuroblastoma in 5 additional cohorts." (PMID 32629858, 2020). "This can occur either directly, since let-7 can target MYCN, or through activation of ras-related nuclear protein (RAN), which leads to increased transcription and phosphorylation of aurora kinase A (AURKA) and subsequent upregulation of MYCN, as shown in neuroblastoma." (PMID 32601913, 2020). "To check whether this effect could be recapitulated in other neuroblastoma cells, we ectopically expressed inducible N-Myc in three additional human neuroblastoma cell lines without MYCN gene amplification, SK-N-AS, SK-N-SH and SY5Y." (PMID 32346009, 2020). "In 1986, it was also shown that retinoblastoma tumor formation was not necessarily dependent on the oncogene MYCN, which was commonly amplified and highly expressed in retinoblastomas (as in neuroblastoma) that had lost RB1, likely contributing to tumor progression but not initiation." (PMID 31683923, 2019). "In addition, most neuroblastoma patients typically have metastatic disease at the time of diagnosis; therefore, MYCN tests were not then performed on those patients." (PMID 31619207, 2019). "In particular, survivin is a prognostic marker in neuroblastoma patients with non-amplified MYCN." (PMID 30609639, 2019). "Moreover, MYCN and FACT expression formed a positive feedback loop in neuroblastoma cells." (PMID 31396265, 2019). "Since a profound PTHLH downregulation was not achieved, presumably because it compromises neuroblastoma cell viability, and to further validate MYCN downregulation upon PTHLH silencing, LA‐N‐1 cells were transiently transfected with PTHLH small interfering RNA (siRNA)." (PMID 31293052, 2019). "We therefore examined whether N-Myc and c-Myc modulated JMJD6 gene expression in CHP134 (chromosome 17q21-ter/JMJD6 gained and MYCN amplified) and SK-N-AS (chromosome 17q21-ter/JMJD6 gained and MYCN-non-amplified) neuroblastoma cells." (PMID 31346162, 2019). "Here our analyses of RNA sequencing data identify the long noncoding RNA lncNB1 as one of the transcripts most over-expressed in MYCN-amplified, compared with MYCN-non-amplified, human neuroblastoma cells and also the most over-expressed in neuroblastoma compared with all other cancers." (PMID 31690716, 2019). "Therefore, we deduced that CTNNA2 is a potential tumor suppressor in neuroblastomas that lacked MYCN expression." (PMID 31489113, 2019). "Interestingly, MYCN and FACT expression formed a positive feedback loop in neuroblastoma cells." (PMID 31396265, 2019).
neuroblastoma (continued). "Importantly, by using the SEQC-498 cohort, we performed a differential RNA expression analysis of the MYCN-amplification and nonamplification neuroblastoma tumors." (PMID 31856871, 2019). "Collectively, targeting a combination of MYCN-targeted genes that interrupts the interconnection of metabolic pathways may overcome drug toxicity and improve the efficacy of current therapeutic agents in MNA neuroblastoma." (PMID 31624245, 2019). "MYCN upregulation is also observed at a higher frequency in several other pediatric solid tumors including Wilms tumor, rhabdomyosarcoma, and retinoblastoma, although generally not to the extent seen in neuroblastoma." (PMID 31616462, 2019). "High-MKI neuroblastoma patients showed a poor survival irrespective of MYCN amplification." (PMID 29464082, 2018). "Moreover, two novel bona fide neuroblastoma oncogenes have been identified, ALK and LIN28B, that are sufficient to drive tumor formation when overexpressed in the neural crest or seem to increase the oncogenic potential of MYCN overexpression." (PMID 29492199, 2018). "Metabolic profiling can also discriminate between MYCN-amplified and non-amplified neuroblastoma cell lines and previous work by others has shown that it may be a useful method to distinguish stage." (PMID 29541417, 2018). "However, the prognostic effect of MYC-family protein expression on these neuroblastomas is less understood, especially when MYCN is not amplified." (PMID 29464082, 2018). "Since a subset of MYCN-non-amplified neuroblastomas have been shown to exhibit deregulated expression of (c)-MYC46, we investigated the expression of MYCN and MYC as well as total level of MYC-family proteins in the six cell lines using antibodies specific for MYCN, MYC or pan-MYC." (PMID 29968736, 2018). "A further study of MYCN, by this time conducted in a murine cell line of neural crest progenitor cells, showed that stable overexpression of either MYCN or ALKF1174L in combination with the absence of cMyc activity leads to the development of a neuroblastoma-like tumor in mice." (PMID 30116755, 2018). "It has been shown in the neuroblastoma cell line IMR-32 that the knockdown of L1CAM leads to a decrease in the formation of tumorospheres, a decrease in the proliferation and migration of tumor cells, and downregulation of MYCN and upregulation of the PTEN tumor suppressor." (PMID 30116755, 2018). "Furthermore, similar as to the ESC miRNA signature, ESC mRNA signature scores are related to survival in a global cohort of neuroblastoma tumors, but also in a subgroup of stage 4 tumors without MYCN amplification." (PMID 30504901, 2018). "We extracted gene expression data obtained during the TARGET research project for the 247 neuroblastoma tissue samples, among them 68 had and 175 did not have MYCN amplification, for four additional samples the amplification status was unknown." (PMID 29137381, 2017).
neuroblastoma (continued). "Of the five stage 3 neuroblastomas in our prior series, microvessel integrin αvβ3 expression was high in the three MYCN-amplified tumors (mean 87% of microvessels, 95% CI 79%–94%), but low in the two MYCN-non-amplified ones (mean 20% of microvessels)." (PMID 28881723, 2017). "Given that IMR-32 cells are a MYCN amplified neuroblastoma cell line, and SK-N-AS cells are a non-MYCN amplified cell line, we compared splice variant content within other MYCN-amplified cell lines (CHLA-122 and SMS-KAN) and non-MYCN-amplified cell lines (LA-N-6 and CHLA-15)." (PMID 28035057, 2017). "Additionally, not all neuroblastoma patients with MYCN-amplified tumors have poor prognoses; those with early clinical disease stages and hyperdiploid karyotypes were still had favorable outcomes." (PMID 27966455, 2017). "This panel was also representative of the whole group in that it was comprised of stage 3 neuroblastomas with MYCN amplification or without it, with unfavorable or favorable Shimada histology, and tumors from patients who survived their tumors or succumbed to them." (PMID 28881723, 2017). "Moreover, another recent study evaluated differential expression profiles of lncRNAs and protein-coding genes between MYCN amplified and non-amplified neuroblastomas by examining microarray and RNA-seq datasets." (PMID 28178969, 2017). "Amplification of MYCN or constitutive up-regulation of MYC protein is observed in approximately half of high-risk tumors; our findings indicate a novel role of TAMs as inducers of MYC expression in neuroblastomas lacking independent oncogene activation." (PMID 29207662, 2017). "Patients with MYCN-non-amplified/unfavorable histology neuroblastomas, who would be expected to have prognosis intermediate between these two groups, showed similar numbers of tumors with diffuse PTEN staining (n = 6, 46%) as with focal or negative PTEN staining (n = 7, 54%)." (PMID 28881723, 2017). "Interestingly, 83% (19 of 23) of the MYCN-non-amplified/favorable histology neuroblastomas showed diffuse PTEN expression, whereas only 18% (3 of 17) of the MYCN-amplified/unfavorable histology tumors showed this diffuse expression of PTEN." (PMID 28881723, 2017). "Furthermore, these studies also assessed the ability of these agents to induce apoptosis in neuroblastoma cells with and without MYCN overexpression." (PMID 27678372, 2016). "The IC50 of topotecan was determined in non-MYCN and MYCN amplified neuroblastoma cell lines." (PMID 26934655, 2016). "Moreover, by considering only neuroblastoma patients who showed relapse or progression of the disease and no MYCN amplification, lower expression of miR-181c was significantly associated with a worse prognosis (χ2 = 8.29, df = 1, p-value = 4.0e-03, n = 120)." (PMID 27829219, 2016). "By using adenoviral gene transduction of the carboxyl-terminal domain of FAK (AdFAK-CD), FAK phosphorylation was decreased and AdFAK-CD decreased neuroblastoma cell proliferation, with a larger proportional decrease in proliferation of MYCN-amplified cells than MCYN non-amplified cells." (PMID 26771642, 2016). "Thus, knockdown of cohesin subunits and MYCN overexpression synergistically inhibit neuroblastoma cell growth, but this effect is not mediated by gross changes in the cell-cycle distribution of the population." (PMID 27539729, 2016). "Moreover, the marked anti-tumor activity of DpC was independent of MYCN amplification, which is a key oncogene and prognostic indicator in neuroblastoma." (PMID 27678372, 2016). "Our results indicate that PI3K inhibitors with weak activity against mTOR fail to target MYCN protein, implying that activity of the PI3K complex may not play a major role in stabilization of MYCN protein in neuroblastoma cells." (PMID 27438153, 2016).